JAK2 (Janus kinase 2)
Diseases named in the same sentence as JAK2 in open-access papers (continued):
Sharing a sentence is not in itself a finding about the gene and the disease.
prostate carcinoma (continued). "Given the pivotal role of PRLR and JAK2/STAT3 signaling in hormone - dependent cancers, exploring their regulatory mechanisms in prostate cancer is vital for developing new treatments." (PMID 40978029, 2025). "Bioinformatics analysis was then performed to assess the relationship between the expression levels of PRLR, JAK2, and STAT3 genes and the survival of prostate cancer patients." (PMID 40978029, 2025). "The JAK2/STAT3 signaling pathway plays a crucial role in various cancers, including prostate cancer." (PMID 40978029, 2025). "In prostate cancer cells, the expression of SHMT2 is upregulated under the regulation of the typical JAK2/STAT3 pathway, affecting the early inflammatory response of cancer." (PMID 38594513, 2024). "Previous studies have demonstrated that the JAK2/STAT3 pathway regulates PD-L1 expression in various cancers, including head and neck squamous, lung, gastric, and prostate cancers." (PMID 39781272, 2024). "Janus kinase 2/signal transducer and activator of transcription 3 (JAK2/STAT3) signaling pathway plays an important role in a variety of cancers, including prostate cancer, hematological malignancies, and liver cancer." (PMID 38185661, 2024). "Specific tyrosine kinase pathways in the development of prostatic cancer, including the activation of EGFR, ephrin type-A receptor 2, and JAK2, have been identified in a mouse model." (PMID 38136890, 2023). "IST5-002 is a small molecule inhibitor that prevents both JAK2 and BCR-ABL-mediated phosphorylation of STAT5 and induces apoptosis in prostate cancer and chronic myeloid leukemia." (PMID 36232600, 2022). "Pacritinib, a JAK2 and FTL3 inhibitor, is currently in phase 2 clinical trials for prostate cancer (Clinical trial number: NCT04635059)." (PMID 36232600, 2022). "For example, JAK2/STAT5B promotes tumor proliferation and metastasis in breast and prostate cancers." (PMID 35244291, 2022). "PTP1B (also known as PTPN1) is a protein tyrosine phosphatase, whose expression is amplified by androgens in prostate cancer cells and which dephosphorylates IGFR, Jak2, and Tyk2, kinases crucial to cytokine signaling pathways." (PMID 31118931, 2019). "For example, prostate cancer cells express high levels of IL-6, EGF, and EGFR, leading to constitutive activation of JAK2 or Src, which in turn results in STAT3 activation through autocrine and paracrine mechanisms." (PMID 24260381, 2013). "While previous research indicated that CDN selectively inhibits JAK2-but not JAK1-in prostate cancer models." (PMID 41585878, 2025). "However, our research also revealed that Osthole can exert anti-prostate cancer effects by binding to PRLR, thereby inhibiting the JAK2/STAT3 pathway." (PMID 40978029, 2025). "In prostate cancer treatment, the PRLR and JAK2/STAT3 signaling pathways are crucial targets." (PMID 40978029, 2025). "However, some OSRE genes, like JAK2 and PLCG2, were shared across liver, lung, and prostate cancers." (PMID 39594421, 2024). "This condition could constitute the breeding ground for the evolution of prostate cancer towards a more aggressive form (G9), involving a change in SHMT2 and PKM2 status through the IL-6/JAK2/STAT3 pathway." (PMID 31500219, 2019). "Interestingly, it has been reported that AGK overexpression promotes aggressiveness in prostate cancer cells through activation of EGFR, and that upregulation of AGK promotes the stem cell-like phenotype in ESCC by sustaining JAK2 activity." (PMID 24886245, 2014). "ATL II also suppresses the proliferation and induces death of human prostate cancer cells DU145 and LNCaP, and arrests the cell cycle in the G2/M phase through mechanisms that possibly relate to AR inhibition, PIAS1 activation, and inhibition of the JAK2/STAT3 signaling pathway." (PMID 37241729, 2023).
prostate carcinoma (continued). "During chemotherapy or radiotherapy for prostate cancer, damage to the cavernous nerve, a postganglionic branch of the pelvic ganglion, may lead to ED, and brain-derived neurotrophic factor (BDNF) promotes nerve regeneration by activating the JAK2/STAT pathway in Schwann cells." (PMID 37407943, 2023). "The results of a recent study suggested that extracellular PRL enhanced NSCLC cell proliferation and promoted JAK2/STAT3 signaling activity through GHR, but not PRLR as previously reported in breast and prostate cancers." (PMID 34487971, 2021). "However, whether Osthole exerts its anticancer effects in prostate cancer by modulating PRLR and the JAK2/STAT3 signaling axis has not been thoroughly investigated." (PMID 40978029, 2025). "Thus, JAK2 and STAT3 may not directly contribute to prostate cancer progression but could modulate the immune tumor microenvironment, thereby promoting disease development." (PMID 40978029, 2025).
multiple myeloma (66 papers, 2010 to 2025). "JAK kinases, mainly JAK1 and JAK2, have been found to participate in the pathogenesis of multiple myeloma, a malignancy susceptible to Bortezomib that can develop resistance as well." (PMID 40699751, 2025). "Of those 39 patients receiving therapeutic agents with a known higher risk of HZ reactivation (immunomodulators, JAK-2-Inhibitors, proteasome inhibitors, long-term chronic steroid) all were treated for Multiple Myeloma." (PMID 36011181, 2022). "We showed that GAC 17:1 treatment causes substantial abrogation of JAK2 phosphorylation level in a time-dependent manner that may be directly implicated in its STAT3 inhibitory effects in multiple myeloma cells." (PMID 28208828, 2017). "A promising example is AZD1480, which blocks cell proliferation at low micromolar concentrations and induces apoptosis in myeloma cell lines via concomitant inhibition of the phosphorylation of signaling proteins JAK2, STAT3, and MAPK." (PMID 37373437, 2023). "Study reported that lncRNA nuclear-enriched abundant transcript 1(NEAT1) sponged miR-214 to target regulation B7-H3 thereby promoted M2 macrophage polarization via phosphorylating JAK2/STAT3 signaling in multiple myeloma." (PMID 36153596, 2022). "A high HO-1 expression level in bone marrow stromal cells can trigger multiple resistances by targeting the JAK2/STAT3 pathway in myeloma." (PMID 36428612, 2022). "It has been shown to effectively suppress myeloma cell growth via Stat3 and Jak2 inhibition, and it has potential as a treatment for RA and other autoimmune diseases." (PMID 34680353, 2021). "We examined the correlation of JAK2 expression in BM megakaryocytes with clinical outcomes of myeloma patients." (PMID 32628819, 2020). "Compared to myeloma patients with low and medium JAK2 IHC score, patients with high JAK2 IHC score showed a signficantly worse OS and a trend for worse PFS." (PMID 32628819, 2020). "JAK2 expression was detectable in the majority of MM patients and correlated with myeloma disease stage." (PMID 32628819, 2020). "An earlier study reported that EP can potentially induce the antitumor effects in multiple myeloma U266 cells; simultaneously, it can act as an antiangiogenic agent through the targeting of the JAK2/STAT3 signaling pathway." (PMID 30781890, 2019). "TQ also found to impede constitutive and IL-6-inducible STAT3 phosphorylation in U266 multiple myeloma cells, as well as inhibit c-Src and JAK-2 activation." (PMID 28983249, 2017). "We found that GAC 17:1 inhibited both constitutive and IL-6-inducible STAT3 activation in multiple myeloma cells along with the abrogation of c-Src and JAK2 activation and the induction of PTEN and SHP-1 proteins." (PMID 28208828, 2017). "In INA-6 cells and primary myeloma cells, janus kinase 2 (JAK-2) and extracellular signal regulated kinase 1 and 2 (ERK-1/2) were phosphorylated by rhEPO treatment." (PMID 27581518, 2016). "Down regulation of the antiapoptotic protein Bcl-XL has been reported in myeloma and U251 cells with JAK2 inhibition, but curiously, in our patient derived GSC tumorspheres down-regulation of Bcl-XL was not apparent in the Western blot analysis we performed." (PMID 26283544, 2015). "Consistently, we confirmed anti-myeloma effect of icaritin in human primary MM xenograft mouse model by down-regulating the levels of p-JAK2, p-STAT3 and VEGF." (PMID 25865044, 2015). "Our case eliminates the possibility of imatinib as the sole cause since our patient received a diagnosis of simultaneous plasma cell myeloma, CML, and a Jak2 mutation positive myeloproliferative disorder (MPD) arising de novo, prior to any treatment." (PMID 25386371, 2014). "Our findings demonstrate that EP can exert antitumor activity in multiple myeloma U266 cells by anti-angiogenic activity targeting JAK2/STAT3 signaling pathway as a potent anti-cancer agent for multiple myeloma treatment." (PMID 22260501, 2012).
multiple myeloma (continued). "6-OAP abrogates the protective effects of IL-6 and IGF-I on myeloma cells through inhibition of Jak2/Stat3 and Akt signal pathways, respectively." (PMID 21755010, 2011). "Thus, HSP90 inhibitors like geldanamycin or zelavespib (PU‐H71) have proven their value in the treatment of myeloma and other cancers, as well as in murine models of JAK2‐V617F and MPL driven MPNs." (PMID 38104968, 2024). "For example, in multiple myeloma, paracrine cytokine stimulation occurs as a result of myeloma cells interacting with bone marrow, resulting in increased production of IL-6, which activates JAK2 and STAT3, all of which are required for proliferation and survival." (PMID 36008987, 2022). "In a conclusion, lncRNA MSTRG.29039.1 could promote proliferation by sponging hsa-miR-12119 via the JAK2/STAT3 pathway in multiple myeloma." (PMID 34422217, 2021). "JAK2 expression correlated with myeloma disease stage (P = .0071)." (PMID 32628819, 2020). "Out of 99 patients, only 1 (1.01%) patient had JAK2 expression on CD138 + myeloma cells." (PMID 32628819, 2020). "Additionally, IL-6 induced STAT3 phosphorylation in U266 multiple myeloma cells were found inhibited by TQ along with c-Src and JAK-2 activation." (PMID 28983249, 2017). "Taken together, this study identified a novel oral JAK2/STAT3 inhibitor that could be developed as an anti-myeloma agent." (PMID 26814430, 2016). "It has been established that interleukin-6 (IL-6) is the most important survival and growth factor in myeloma cells and regulated at least 3 pathways, namely JAK2/STAT3, MAPK/ERK, and PI3K/AKT, thus targeting IL-6-mediated signaling pathways is a promosing therapeutic strategy in MM." (PMID 25865044, 2015). "The TrkB signaling pathway overlaps with the ERK/MAPK or JAK2/STAT3 signaling pathway in myeloma or endometrial cancer cells, which prompted us to examine whether TrkB suppressed miR-204-5p expression via these signaling pathways." (PMID 24321270, 2013). "After the discovery of the JAK2 V617F mutation in MPN patients, several other mutations in the JH2 domain of JAKs have been identified in MPN, but also in lymphoid and myeloid leukemia and multiple myeloma patients." (PMID 21533163, 2011). "Here, Stattic and WP1066 were used as positive control to detect their effects on apoptosis in HCT116 colon cancer and U266 multiple myeloma cells, which conformed the JAK2/STAT3 pathway may be an important target to induce the apoptosis of cancer cells." (PMID 20712901, 2010). "Therefore, we thought that it could be one of the effective treatment protocols if the activated STAT3 and JAK2 signals in multiple myeloma can be controlled with radotinib." (PMID 35503759, 2022). "Therefore, we may postulate that icaritin can exert anti-myeloma effects in vivo via suppressing “p-JAK2/p-STAT3/VEGF”-mediated signaling pathway." (PMID 25865044, 2015). "A study demonstrated that crocin can mediate the suppression of STAT3 and inhibit the upstream kinases JAK1, JAK2, and SRC, thereby preventing the progression of multiple myeloma." (PMID 40841966, 2025). "Preclinical study in multiple myeloma models revealed that FT suppressed the STAT3/5-DNA binding capacity while simultaneously inhibiting the activation of upstream kinases JAK1, JAK2 and Src." (PMID 40841966, 2025). "Research has identified miR-451a as a regulator of the IL6R gene and an activator of the JAK2/STAT3 pathway, which regulates the proliferation and apoptosis of multiple myeloma cells." (PMID 39129166, 2025). "In conclusion, radotinib inhibits multiple myeloma cell proliferation via suppression of STAT3, JAK2 and c-Myc signaling." (PMID 35503759, 2022).
multiple myeloma (continued). "One of the best characterized pathways in this regard is the downregulation of the JAK2/STAT3 signaling pathway by increased SOCS3 expression, as described in multiple myeloma." (PMID 34204116, 2021). "In MM, JAK2 inhibitor TG101209 and PI3K inhibitor LY194002 combination displayed synergistic cytotoxicity against myeloma cells." (PMID 34680295, 2021). "Previous studies have shown that SOCS3 inhibits the JAK2/STAT3 pathway in hepatocyte and multiple myeloma cells." (PMID 34765550, 2021). "Leelamine from pine’s bark attenuated phosphorylation of upstream JAK1/JAK2/Scr macromolecules and downstream STAT3, hence evoking myeloma cell cycle arrest and apoptosis." (PMID 34680295, 2021). "A recent study showed that B7-H3 was involved in the activation of JAK2/STAT3 via redox-mediated oxidation and activation of Src in multiple myeloma cells." (PMID 32127943, 2020). "In particular, guggulsterone abrogated the stimulation of c-Src and JAK2 and therefore inactivates STAT3 in human multiple myeloma cells." (PMID 32545187, 2020). "The analysis of the whole transcriptome data revealed different expression levels of several genes, such as JAK1, JAK2, JAK3, RAF, IL6R, NCAM (CD56), WHSC1, MCL1, BCL2, and IGF1, which showed myeloma pathogenesis." (PMID 30079703, 2019). "JAK2/STAT activation has been observed in several types of cancer and tumours, including multiple myeloma, leukaemia, prostate cancer, breast cancer, and colon cancer." (PMID 29984230, 2018). "Ramakrishnan’s study examined the pre-clinical activity of the JAK2 inhibitor TG101209, which induced dose- and time-dependent cytotoxicity in a variety of multiple myeloma cell lines." (PMID 29290986, 2017). "Increases in phosphorylation of ERK-1/2 and JAK-2 were observed, suggesting that the EPO/EPOR signaling complex is functional in myeloma cells." (PMID 27581518, 2016). "Examination of primary myeloma cells for their putative active EPO/EPOR signaling revealed that all samples (MM-51-MM-54) exhibited activation of both ERK-1/2 and JAK-2 after 5 min treatment with 10 U/ml rhEPO." (PMID 27581518, 2016). "Rhee and co-worker have reported that ergosterol peroxide inhibited the signaling pathway proteins JAK2/STAT3, which are important in angiogenesis, and exerted anti-tumor activity in multiple myeloma U266 cells." (PMID 27058618, 2016). "Compared to CD45- myeloma cells, CD45+ myeloma cells with an activated JAK/STAT3 pathway are particularly sensitive to JAK2 inhibitor which inhibits IL-6-induced JAK and STAT3 phosphorylation." (PMID 25781885, 2015). "We further evaluated the potential effects of icaritin on the status of JAK2 and STAT3, which are frequently activated in myeloma cells." (PMID 25865044, 2015). "Corresponding to the immunohistochemistry changes, western blot analysis showed icaritin was able to down-regulate significantly the expression of p-JAK2, p-STAT3 and VEGF proteins in myeloma tissue." (PMID 25865044, 2015). "Icaritin suppressed the expression of p-JAK2, p-STAT3 as well as VEGF in myeloma tissue evaluated by immunohistochemistry and western blot, which were consistent with the results of in vitro experiments." (PMID 25865044, 2015). "A research study reported that the inhibition of the activation of upstream JAK1, JAK2, and c-Src kinases suppressed the downstream STAT3 in human multiple myeloma cells." (PMID 25405202, 2014). "FLLL32 was also more potent than curcumin to inhibit STAT3 Y705 and JAK2 phosphorylation in U266 and ARH-77 multiple myeloma cell lines." (PMID 20712901, 2010). "In addition, the proliferation of myeloma cells was potently inhibited in vitro and in vivo secondary to the inhibition of phosphorylated FGFR3, phosphorylation of Jak2 and Stat3 and Cyclin D2 by AZD1480." (PMID 34680353, 2021). "JAK2 could be phosphorylated by recombinant EPO in kinase assay and EPO exposure intriguingly reduced myeloma cell survivals." (PMID 34680295, 2021).
multiple myeloma (continued). "JAK2 expression did not correlate with the presence or the degree of BMF, nor the cytogenetics or myeloma cell differentiation, but was significantly associated with ISS stage." (PMID 32628819, 2020). "For example, nifuroxazide, a drug used to treat diarrhea, could effectively inhibit JAK2 and TYK2, while decreasing the p-STAT3 levels in multiple myeloma." (PMID 32545187, 2020). "Treatment of myeloma cells with EPO was followed by JAK-2 and ERK-1/2 phosphorylation while knockdown of EPOR expression in the myeloma cell line INA-6 reduced JAK-2 and ERK-1/2 phosphorylation, again demonstrating the specificity of active EPO/EPOR signaling in myeloma cells." (PMID 27581518, 2016). "Furthermore, inhibition of constitutive STAT3 signaling by the JAK2 inhibitor, AG490 suppressed the growth, and decreased the invasion of human hepatocellular carcinoma cells, and also induced apoptosis in multiple myeloma cells." (PMID 20712901, 2010). "Moreover, a significant reduction of phospho-JAK2 and Src, the upstream tyrosine kinases of STAT3, was observed in Icariside II-treated U937 cells in a dose- and time-dependent manner, which was similarly supported by our previous report in multiple myeloma cells." (PMID 22493659, 2012). "SAR317461, a small molecule inhibitor of JAK2 identified by structure-based drug design, was used as it has been shown to potently down-regulate expression of phosphorylated JAK2 and STAT1 without affecting expression of total JAK2 and STAT1 in multiple myeloma cell lines." (PMID 22697788, 2012).